EFCAB11 (EF-hand calcium binding domain 11)
Synonyms: C14orf143
Tractability: PROTAC: ubiquitination databases record sites on it.
Gene: Protein-coding gene on chromosome 14 (89,794,669 to 89,954,777, reverse strand). Ensembl gene ENSG00000140025.
Subcellular location (Human Protein Atlas): Cell Junctions; Cytosol
Gene Ontology:
Molecular function: protein binding; enzyme regulator activity; calcium ion binding
Biological process: microtubule cytoskeleton organization
Genetic constraint (gnomAD): Loss-of-function variants: 14 observed, 20.64 expected, observed/expected ratio (o/e) 0.68, 90% interval 0.45 to 1.06. The upper end of that interval is the gene's LOEUF score, 1.06, which puts it in group 4 of 6, group 1 being the genes least tolerant of losing a copy. Missense variants: 188 observed, 197.97 expected, observed/expected ratio (o/e) 0.95, 90% interval 0.84 to 1.07. Synonymous variants: 65 observed, 69.52 expected, observed/expected ratio (o/e) 0.94, 90% interval 0.76 to 1.15.
Homologues: Orthologues: chimpanzee EFCAB11 (100% identical), macaque EFCAB11 (86% identical), guinea pig EFCAB11 (82% identical), rabbit EFCAB11 (82% identical), pig EFCAB11 (81% identical), rat Efcab11 (79% identical), mouse Efcab11 (77% identical), dog EFCAB11 (63% identical), tropical clawed frog efcab11 (52% identical), zebrafish efcab11 (48% identical).
Diseases named in the same sentence as EFCAB11 in open-access papers:
EFCAB11 is named in the same sentence as 3 diseases in open-access papers, as found by Europe PMC text mining. Sharing a sentence is not in itself a finding about the gene and the disease. The quoted sentences say what the papers report.
multiple system atrophy (2 papers, 2020 to 2023). Multiple system atrophy (MSA) is a neurodegenerative disorder characterized by autonomic failure (cardiovascular and/or urinary), parkinsonism, cerebellar impairment and corticospinal signs with a median survival of 6-9 years. "One research group found EFCAB11 to be overexpressed in brain samples of patients with multiple system atrophy, another type of neurodegenerative disorder." (PMID 37953885, 2023). "Another research group performed circRNA sequencing of the brain samples from multiple system atrophy (MSA) patients and identified five circRNAs, namely IQCK, MAP4K3, EFCAB11, DTNA, and MCTP1, that were overexpressed in the white matter of the cortical tissue." (PMID 33269108, 2020).
diabetes (1 paper, 2025). "A transmembrane protein gene, TMEM204, typically hypomethylated in MASLD patients, was found to be hypermethylated, and EFCAB11, often downregulated in obese individuals with diabetes, showed similar hypermethylation in prenatal-BPA treated liver samples." (PMID 40914344, 2025).
EFCAB11 also shares sentences with these, for which no sentence is quoted: hepatocellular carcinoma (1 paper).